CSRNP2 (cysteine and serine rich nuclear protein 2)
Description:
Binds to the consensus sequence 5'-AGAGTG-3' and has transcriptional activator activity (By similarity). May play a role in apoptosis.
Synonyms: TAIP-12; C12orf22; FAM130A1; C12ORF2; PPP1R72
Tractability: PROTAC: ubiquitination databases record sites on it.
Gene: Protein-coding gene on chromosome 12 (51,061,205 to 51,083,664, reverse strand). Ensembl gene ENSG00000110925.
Subcellular location: Nucleus
Subcellular location (Human Protein Atlas): Nuclear speckles
Gene Ontology:
Molecular function: phosphatase binding; protein binding; DNA-binding transcription factor activity; DNA-binding transcription factor activity, RNA polymerase II-specific; sequence-specific DNA binding; DNA-binding transcription activator activity, RNA polymerase II-specific
Biological process: positive regulation of transcription by RNA polymerase II; regulation of transcription by RNA polymerase II
Cellular component: nucleus; chromatin
Genetic constraint (gnomAD): Loss-of-function variants: 12 observed, 41.72 expected, observed/expected ratio (o/e) 0.29, 90% interval 0.18 to 0.47. The upper end of that interval is the gene's LOEUF score, 0.47, which puts it in group 2 of 6, group 1 being the genes least tolerant of losing a copy. Missense variants: 483 observed, 719.12 expected, observed/expected ratio (o/e) 0.67, 90% interval 0.62 to 0.72. Synonymous variants: 248 observed, 289.4 expected, observed/expected ratio (o/e) 0.86, 90% interval 0.77 to 0.95.
Homologues: Orthologues: chimpanzee CSRNP2 (99% identical), macaque CSRNP2 (99% identical), guinea pig CSRNP2 (94% identical), pig CSRNP2 (94% identical), dog CSRNP2 (94% identical), rabbit CSRNP2 (91% identical), rat Csrnp2 (91% identical), mouse Csrnp2 (90% identical), tropical clawed frog csrnp2 (60% identical), zebrafish csrnp2 (47% identical), Drosophila melanogaster Axud1 (31% identical), Caenorhabditis elegans C41D11.3 (21% identical). Paralogues in human: CSRNP3 (48% identical), CSRNP1 (31% identical).
Diseases named in the same sentence as CSRNP2 in open-access papers:
CSRNP2 is named in the same sentence as 6 diseases in open-access papers, as found by Europe PMC text mining. Sharing a sentence is not in itself a finding about the gene and the disease. The quoted sentences say what the papers report.
Obesity (2 papers, 2013 to 2021). Accumulation of substantial excess body fat. "CSRNP2 has been positively associated with many aberrant non-cancerous diseases, including obesity and type 2 diabetes mellitus." (PMID 33869003, 2021). "Eight genes (BCAT1, BMP2 K, CSRNP2, MYNN, NCKAP5L, SAP30BP, SLC35B4, and SP1) were isolated as candidates for obesity." (PMID 24455749, 2013). "The rest of the candidates, C2orf15, DENND1B, MRPL30, POC1B, RP4-655J12.3, TMBIM4, BMP2 K, CSRNP2, NCKAP5L, TOMM5, and BAP1, may be novel genes related to T2DM or obesity." (PMID 24455749, 2013).
influenza infection (1 paper, 2007). "Preliminary studies indicate that CSRNP-2 deficient mice were more susceptible to influenza infection (data not shown), but it appears that it does not affect the generation of influenza virus-specific T cells." (PMID 17726538, 2007).
cancer (1 paper, 2020). A tumor composed of atypical neoplastic, often pleomorphic cells that invade other tissues. "Among the differentially expressed genes, 5 (DUSP6, SOX9, DKK1, ARRDC3 and CSRNP2) were known to be associated with signaling pathways in cancer or cancer stem cells." (PMID 32231719, 2020).
tumor (1 paper, 2021). "Meanwhile, CSRNP2 and CSRNP3 were both mostly positively associated with effector memory CD4 T cells, but not with type 2 T cells in tumor tissues." (PMID 33869003, 2021).
CSRNP2 also shares sentences with these, for which no sentence is quoted: Alzheimer disease (1 paper); type 2 diabetes mellitus (1).